INS (insulin)
Diseases named in the same sentence as INS in open-access papers (continued):
Sharing a sentence is not in itself a finding about the gene and the disease.
Hyperglycemia (continued). "In skeletal muscle-specific whole-body (KO) of USP21 the hyperglycemia induced by high-fat feeding for 9 weeks was significantly attenuated, while insulin sensitivity was improved." (PMID 40806701, 2025). "As additional objectives for evaluating CGM metrics, we expected a reduction in the time spent in hypo‐ and hyperglycemia in the education group, attributable to more precise carbohydrate counting and improved capability for flexible insulin dosing." (PMID 40121673, 2025). "Macrosomia, in particular, is more frequently associated with HNF4A-MODY due to its impact on fetal insulin secretion, but has also been occasionally reported in HNF1A-MODY, potentially reflecting unrecognized maternal hyperglycemia." (PMID 41367630, 2025). "In case maternal metabolism is not adapted to these needs, instead of a mild reduction, there is a vast decrease in insulin sensitivity, resulting in fetal hyperglycemia and overgrowth." (PMID 40559375, 2025). "This pharmacokinetic profile contrasts markedly with the rapid hypoglycemic nadir and rebound hyperglycemia observed with a standard subcutaneous insulin bolus, highlighting the patch’s potential for mitigating hypoglycemia." (PMID 41471093, 2025). "Vitamin C has been reported to improve pancreatic beta cell function and insulin sensitivity, leading to control of hyperglycemia, a finding that is consistent with the findings of the present study." (PMID 40735405, 2025). "Hyperglycemia, characterized by elevated blood glucose levels, leads to increased insulin production—a condition known as hyperinsulinemia." (PMID 40678416, 2025). "Pregnant women with hyperglycemia generally exhibit a higher overall incidence of requiring insulin therapy, which increases with maternal age, and women over 35 years old have a significantly higher probability of undergoing cesarean delivery." (PMID 40958678, 2025). "Some patients with only postprandial glycaemic excursions were managed with bolus insulin alone, while those with fasting hyperglycaemia required basal insulin." (PMID 40430241, 2025). "Although the present study lacks data on insulin levels, the results showed that the A. oligophyllus extract not only controlled hyperglycemia and hyperlipidemia in pregnant diabetic rats but also increased the mass of their pancreatic cells." (PMID 41237113, 2025). "An 80-year-old female from Norfolk Island was referred to an Australian quaternary hospital after a prolonged local admission for uncontrolled hyperglycemia despite escalating insulin doses." (PMID 40860576, 2025). "Preclinical models have indicated that fenofibrate mitigates beta cell stress at hyperglycaemia via mechanisms that reduce insulin secretion." (PMID 39477880, 2025). "Chronic Cd exposure can result in hyperglycaemia, decreased insulin sensitivity in muscle and liver, impaired lipid metabolism, and reduced leptin levels." (PMID 41488239, 2025). "When these patients developed hyperglycemia, they immediately received subcutaneous insulin injections and symptomatic treatment." (PMID 40771932, 2025). "Chronic hyperglycemia leads to decreased insulin secretion and increased insulin resistance, a concept commonly referred to as glucose toxicity." (PMID 40649827, 2025). "In a randomized controlled trial, approximately one-third of 49 T2DM patients receiving preoperative carbohydrate loading required insulin intervention, with a perioperative hyperglycemia incidence of 12.2%." (PMID 41572974, 2025). "This improvement is likely due to the effects of HIIT, vitamin D3 injection, or their interaction in increasing insulin sensitivity, improving glucose absorption, and ultimately reducing hyperglycemia." (PMID 40144137, 2025). "As such, disease management is overwhelmingly focused on the maintenance of glucose homeostasis and prevention of hyperglycemia, which have been enabled with advances in continuous glucose monitoring and insulin pumps." (PMID 40429969, 2025).
Hyperglycemia (continued). "Complete ERα deletion as well as ERα gene silencing in the VMN in female mice produce a metabolic syndrome that includes hyperglycemia, glucose intolerance, and insulin insensitivity." (PMID 39911518, 2025). "This inflammatory response, combined with the accumulation of FFAs, further increases insulin resistance in key tissues such as muscles and the liver, exacerbating hyperglycemia." (PMID 40612313, 2025). "In 2016, the patient underwent several cycles of continuous intravenous insulin infusion due to persistent hyperglycemia and DKA despite CSII treatment (HbA1c 78 mmol/mol - 9.3%)." (PMID 40995084, 2025). "Following the correction of hyperglycemia through insulin treatment, the euglycemic diabetic rats exhibited a trend toward normalization of cardiovascular parameters, including SBP, DBP, and HR." (PMID 40564795, 2025). "This response boosts hepatic gluconeogenesis and reduces insulin sensitivity, resulting in hyperglycemia, which agrees with our results." (PMID 40806903, 2025). "This hypoinsulinemia, along with insulin resistance and excessive catabolism due to counter‐regulatory hormones (cortisol, catecholamines, growth hormone, and glucagon), leads to hyperglycemia." (PMID 40931439, 2025). "Insulin, initially isolated over a century ago, remains a critical therapy for the management of hyperglycemia in patients with longstanding T2D or known β-cell failure." (PMID 40870444, 2025). "Beta-cell dysfunction, on the other hand, reflects an inability to compensate for increased insulin demands, particularly during pregnancy, leading to hyperglycemia." (PMID 40658669, 2025). "Daily; educational on hypoglycemia and hyperglycemia management, insulin injections, dosing adaptation, blood glucose level entry, insulin dosage recording, physical activity, and diet logging." (PMID 40051514, 2025). "In IR states, insulin’s ability to suppress hepatic gluconeogenesis and lipolysis is impaired, leading to hyperglycaemia, dyslipidaemia, and hepatic fat accumulation." (PMID 40755010, 2025). "Activation of ERs in the liver impairs insulin signalling and increases gluconeogenesis, leading to hyperglycaemia." (PMID 41488239, 2025). "Insulin therapy is also used to manage hyperglycaemia, where insulin is given by one to three injections per day regimens." (PMID 41404215, 2025). "Peptides secreted by the pancreas, such as insulin and glucagon, play a vital role in maintaining this glucose homeostasis, and an imbalance in it is related to the onset of hyperglycemia and DM." (PMID 39136514, 2025). "The precise mechanisms underlying these changes remain uncertain, possibly resulting from altered placental transport of metabolites, or as secondary consequences of hyperglycemia and compensatory insulin secretion in the fetus." (PMID 39861388, 2025). "It is likely the present study captured more people with extreme hyperglycaemia; indeed two participants were ketotic at screening, indicating high rates of insulin omission." (PMID 40315203, 2025). "Impaired NKA function can disrupt this balance, leading to reduced insulin secretion and contributing to hyperglycemia." (PMID 40046060, 2025). "Studies from the literature show that alloxan-diabetic rats have hyperglycemia due to damaging insulin-secreting cells of the pancreas." (PMID 40365185, 2025). "The HCL system mitigated her overnight hyperglycemia by increasing the basal insulin and resulting in a glucose level of approximately 120 mg/dL the following morning." (PMID 40822948, 2025). "T2D is a chronic metabolic disorder characterized by hyperglycemia, which results from defects in insulin secretion, insulin action, or both." (PMID 40707897, 2025). "Glucose control must balance the risks of hyperglycemia-related complications with the dangers of hypoglycemia, particularly in patients receiving enteral nutrition or insulin infusions." (PMID 41441198, 2025).
Hyperglycemia (continued). "After birth, neonatal exposure to high insulin concentrations is attributed to both maternal hyperglycemia and hyperinsulinemia in the breast milk." (PMID 40077697, 2025). "The ER chaperone, glucose-regulated protein 78 (GRP78), is essential for insulin biosynthesis and enhancing ER chaperone capacity was found to improve β-cell function in the presence of prolonged hyperglycemia." (PMID 40244115, 2025). "This dysfunction in insulin signaling leads to hyperglycemia and a low glucose tolerance, as the glucose uptake by peripheral tissues is impaired." (PMID 40429763, 2025). "The automatic correction bolus accounted for 40–50% of the total bolus insulin and improved hyperglycemia at night." (PMID 40822948, 2025). "Our previous work has demonstrated a dynamic link between autonomic nerve stimulation and insulin secretion during hyperglycemia, and preliminarily indicated that EA at ST25 can partially repair the neurophysiological damage under hyperglycemia." (PMID 40380290, 2025). "Impaired incretin signaling, particularly reduced GLP-1 and gastric inhibitory polypeptide activity, diminishes glucose-stimulated insulin secretion and contributes to hyperglycemia." (PMID 41012437, 2025). "In response to chronic hyperglycemia, β cells increase insulin secretion, which can induce ER and oxidative stress." (PMID 40862756, 2025). "Cana improved metabolic parameters by reducing postprandial hyperglycemia, glucose intolerance, and excessive insulin secretion induced by HFD." (PMID 41031893, 2025). "T2D is induced by pancreatic beta cell dysfunction, i.e., the secretion of insulin is decreased resulting in hyperglycemia." (PMID 39859066, 2025). "Following meals, food intake stimulates endogenous insulin secretion; however, high antibody levels bind to insulin, reducing its bioactivity and leading to postprandial hyperglycemia." (PMID 41585798, 2025). "Chronic elevation of circulating insulin during chronic hyperinsulinemia activates its receptors, thus promoting high hyperglycemia toward lipogenesis." (PMID 40868096, 2025). "Both had insulin‐treated hyperglycemia, severe structural brain defects, dysmorphic features, and lactic acidosis." (PMID 40062559, 2025). "During the initial intensive insulin therapy, the patient’s blood glucose (BG) levels were highly variable, with extreme fluctuations ranging from severe hyperglycemia (361 mg/dL post-meal) to hypoglycemia (38 mg/dL pre-meal)." (PMID 39931500, 2025). "Hyperglycemia-induced fetal hyperinsulinemia plays a central role, as elevated insulin levels stimulate adipocyte proliferation and hypertrophy, leading to increased fat deposition." (PMID 40052691, 2025). "Since PI3Kα inhibition interferes with insulin signaling, hyperglycemia was the most frequent adverse effect of alpelisib in treatment of breast cancer." (PMID 41430313, 2025). "Various strategies have been proposed to manage PI3K inhibitor-induced hyperglycemia, including the administration of exogenous insulin." (PMID 40573322, 2025). "Meanwhile, the patient’s total daily insulin dosage was significantly higher than the estimated dose, and hyperglycemia secondary to hypoglycemia (Somogyi phenomenon) has been ruled out via CGM." (PMID 41019343, 2025). "G6P is trapped in hepatocytes and high insulin levels, commonly administered in the setting of hyperglycemia, activate glycogen synthase enzyme, which converts G6P into glycogen, a stored form of glucose." (PMID 41235379, 2025). "This persistent inflammatory state is predominantly driven by metabolic stresses arising from hyperglycemia and insulin resistance." (PMID 41296433, 2025). "Long-acting agents such as semaglutide, liraglutide, dulaglutide, and exenatide (extended-release) increase insulin secretion and suppress glucagon levels to modulate post-prandial hyperglycemia." (PMID 41393547, 2025).
Hyperglycemia (continued). "In summary, AT inflammation is the key initiating factor driving lipid metabolism disorders, specifically dyslipidemia, and glucose metabolism imbalance, including insulin resistance, hyperglycemia, and AGEs accumulation." (PMID 41246338, 2025). "Hyperglycemia and impaired insulin signaling lessen glucose utilization by skin keratinocytes and disturb their normal proliferation, migration, maturation, and differentiation." (PMID 41377944, 2025). "Previous studies have shown that activation of AMPK enhances glucose uptake and utilization, thereby improving insulin sensitivity and reducing hyperglycemia." (PMID 40475063, 2025). "Although insulin secretion remained high, it was insufficient to maintain glucose homeostasis, resulting in marked hyperglycemia." (PMID 41011571, 2025). "This is consistent with previous findings that insulin therapy can normalize CD8+ T-cell profiles in a rat STZ model in the liver by reducing antigen load and hyperglycemia-associated inflammation." (PMID 41158127, 2025). "After admission in all 153(100%) patients insulin was used to manage hyperglycemia while metformin is used in 31(20.26%) patients in addition to insulin." (PMID 40857346, 2025). "Hypoglycemia and hyperglycemia levels were similar, with reduced insulin use in the sitagliptin groups." (PMID 39939862, 2025). "HMT-rice treatment increased the content of lysophospholipids, which was beneficial for promoting insulin signaling and alleviating hyperglycemia." (PMID 40791231, 2025). "Chronic hyperglycemia contributes to insulin resistance, reduced insulin secretion, and, subsequently, inadequate downregulation of non-insulin-dependent transporters." (PMID 40649827, 2025). "GLP-1RAs bind to the Glucagon-like peptide-1 (GLP-1) receptor to stimulate the pancreas to release insulin in response to in response to hyperglycemia, effectively lowering glucose levels." (PMID 40471297, 2025). "PI3K/AKT pathway inhibition disrupts these processes, leading to reduced glucose uptake, increased gluconeogenesis, and impaired insulin signaling, making hyperglycemia a common side effect of PI3K/AKT inhibitors 15,51–54." (PMID 41345397, 2025). "In conclusion, our study has shown that insulin immunoreactivity in myenteric neurons or their nitrergic subpopulation is gut segment-specific and highly influenced by hyperglycemia in a time-dependent manner." (PMID 40497986, 2025). "While in non-diseased individuals, glucose can be taken by metabolic cells via insulin stimulation, the insulin dysfunction in diabetic patients does not allow for such measures, leading to a pathologic state of hyperglycemia." (PMID 40943351, 2025). "This suggests that the adipocyte‐beta crosstalk leads to greater hyperglycemia‐induced insulin secretion, compared to the modest response in monocultures (p < 0.0001)." (PMID 40746010, 2025). "Hyperglycaemia leads to excessive production of ROS, which damages proteins, lipids, and DNA and impairs insulin signalling and β-cell function." (PMID 41614781, 2025). "Studies also suggest that CBD treatment ameliorates metabolic dysfunctions such as hyperglycemia and increases insulin levels in diabetic rats." (PMID 40283884, 2025). "DM is a condition of chronic hyperglycemia from altered insulin secretion, action or both, that disturbs metabolism of carbohydrate, fats, and protein." (PMID 40843204, 2025). "This indicates that our hyperglycemia cell model exhibits impaired insulin signaling, consistent with findings from diabetic models in previous studies." (PMID 40869265, 2025). "Oral administration of linoleic acid, included in long-chain fatty acid, two hours before an oral glucose tolerance test (OGTT) reportedly ameliorated postprandial hyperglycemia by promotion of insulin secretion via GPR40 pathway in mice." (PMID 39899133, 2025).
Hyperglycemia (continued). "This increased functional demand placed on pancreatic β-cells eventually leads to their inability to maintain compensatory insulin secretion, resulting in progressive hyperglycemia." (PMID 40722870, 2025). "For example, everyday tasks often include monitoring blood glucose, administering insulin through injections or a pump, tracking carbohydrate intake, exercising, organizing supplies, and managing hypo- and hyperglycemia." (PMID 40303942, 2025). "Chronic hyperglycemia in DM results in a decrease in insulin efficiency in promoting glucose uptake and utilization, alongside a reduction in insulin sensitivity, also known as IR." (PMID 40290429, 2025). "The mechanisms of hyperglycemia include an increase in insulin resistance and a reduction in β cell function." (PMID 40735043, 2025). "Down-regulation of the AMPK pathway impairs insulin sensitivity and promotes hyperglycemia, while the opposite effects are induced by AMPK activators." (PMID 40872540, 2025). "Both doses induced significant hyperglycemia, elevated glycated hemoglobin, and reduced insulin levels." (PMID 41361213, 2025). "Transition to SC insulin occurs once acidosis and hyperosmolarity resolve, with a 1-2 hour overlap to prevent rebound hyperglycemia." (PMID 41141170, 2025). "During the CFC, inappropriate insulin and cortisol counterregulatory responses were documented with relative hyperinsulinism in the setting of physiologic hyperglycemia and abonormally low cortisol concentrations in the setting of hypoglycemia." (PMID 40064185, 2025). "A significant increase in CCL2 expression in adipose tissue in an experimental study significantly reduced the ability of insulin to stimulate glucose transport into cells, which led to hyperglycemia and an increase in LDL and triglyceride levels." (PMID 40943138, 2025). "The CME or FCME combination with SHE and metformin showed anti-diabetic effects by regulating insulin secretion and inhibiting hyperlipidemia and hyperglycemia, hence diminishing damage-related liver and kidney enzymes." (PMID 40563879, 2025). "By enhancing glucose-dependent insulin secretion and suppressing glucagon release, these agents reduce chronic hyperglycemia-induced oxidative stress and AGE accumulation, thereby attenuating glomerular basement membrane thickening and albuminuria." (PMID 40534883, 2025). "These disruptions can lead to alterations in glucose production and insulin responsiveness, ultimately resulting in hyperglycemia or elevated blood glucose levels." (PMID 40765566, 2025). "Insulin treatment, carried out until blood glucose is well controlled (between the blue lines), produces a remission of this dramatic hyperglycemia, returning the glucose to its value before the period of high sugar consumption." (PMID 38895272, 2025). "Insulin can increase the risk of CRC by its effect on normal and neoplastic colonic cells and the reduced effect of hyperglycemia on the motility of the colon." (PMID 39018497, 2025). "This interpretation is supported by our prior analysis of the T1DEXI dataset, which showed that individuals with insulin on board (IOB) in the preceding 4 h were significantly more likely to reverse hyperglycaemia with activity." (PMID 41059660, 2025). "Intensive insulin therapy with insulin lispro was initiated on hospital day 4, and the insulin dosage was gradually increased for postprandial hyperglycemia." (PMID 41458730, 2025). "The biological mechanism linking maternal hyperglycemia to fetal pancreatic growth likely involves fetal hyperinsulinemia and insulin-mediated organomegaly." (PMID 40807035, 2025). "Virtually, NOD diabetes mice received IFN‐γ platelets treatments prominently preserved β‐cell integrity and insulin production, ultimately hindering the progress to hyperglycemia." (PMID 40019367, 2025).